IL6 (interleukin 6)
Diseases named in the same sentence as IL6 in open-access papers (continued):
Sharing a sentence is not in itself a finding about the gene and the disease.
tumor (continued). "As a pivotal cytokine in PDAC, IL-6 not only mediates the tumor-stromal crosstalk but also activates downstream oncogenic pathways such as JAK/STAT." (PMID 41463034, 2025). "In the tumour microenvironment, the IL-6/JAK/STAT3 axis is stimulated by release of IL-6 from cells such as TAMs." (PMID 39510801, 2025). "Proinflammatory cytokines, such as tumor necrosis factor (TNF), IL-6, and IL-1β, typically drive tumor progression by enhancing tumor cell proliferation, survival, and invasive potential, as well as promoting angiogenesis." (PMID 40563367, 2025). "Mechanistically, tumor burden positively correlated with postprandial insulin levels (r = 0.62, p < 0.01), hepatic interleukin-6 (IL-6) expression (r = 0.58, p < 0.05), and liver cholesterol accumulation (r = 0.71, p < 0.001)." (PMID 41398969, 2025). "Hp’s VacA exotoxin, found in the lung, stimulates the production of interleukins IL-8 and IL-6 in lung cells, contributing to tumor angiogenesis." (PMID 40563468, 2025). "Persistent activation of the IL-6/STAT3 pathway, for instance, has been implicated in tumor-promoting processes including angiogenesis, epithelial-to-mesenchymal transition (EMT), invasion, and immune evasion." (PMID 41479671, 2025). "For example, 4-methylumbelliferone (4-MU) primarily exerts its anti-tumor effects by regulating inflammatory factors, particularly through the inhibition of IL-6 production and angiogenesis." (PMID 41142809, 2025). "In contrast, in the hypothalamus, the expressions of TNF-α, IL-6, IL-1β and NF-κB were elevated in the Tumor group of mice, which were all reversed by the treatment of PVSO group (p < 0.05)." (PMID 40993108, 2025). "ONX-0914 inhibited tumor progression, reduced immunosuppressive myeloid cells, blocked IL-6/IL-23/IL-17 inflammation, and induced apoptosis." (PMID 41293269, 2025). "IL-6 secreted by CAFs activates the JAK/STAT3 pathway in tumor cells, promoting proliferation via cyclin D1 upregulation." (PMID 41311372, 2025). "Serum IL-6 had a positive correlation with tumor IL-6 expression (ρ = 0.56, p < 0.0001) and an inverse correlation with the CD8/CD163-positive cell count ratio (ρ = −0.4, p < 0.01)." (PMID 39652104, 2025). "Increased regulatory T cells (Tregs) in IAC samples suggested an immunosuppressive trend during tumor progression, potentially regulated by cytokines such as interleukin-6 (IL-6), interleukin-10 (IL-10), and tumor necrosis factor-alpha (TNF-α)." (PMID 41417416, 2025). "iCAF is located at the periphery of the tumor and is characterized by the expression of large amounts of inflammatory mediators and chemokines (i.e., IL‐6), thus chronic inflammation and an immunocompetent environment, a hallmark of cancer." (PMID 40255916, 2025). "According to data from literature, GDF15 and IL-6 are likely produced at the tumor site, composed of cancer cells as well as various infiltrated cell populations in the tumor microenvironment." (PMID 40124481, 2025). "Inflammatory cytokines, such as TNF-α, IL-6, and IL-17, released by immune cells, activate multiple signaling cascades within tumor cells." (PMID 40729026, 2025). "For example, in pancreatic cancer, the upregulation of L1CAM in tumour-associated endothelial cells (TECs) enhanced IL-6 expression, activating the JAK/STAT3 signaling pathway, which in turn triggered EndMT associated with tumour progression and metastasis." (PMID 40083695, 2025). "These adipocytes promote tumor progression, neovascularization, and metastasis by secreting adipokines such as IL6 and leptin." (PMID 40427188, 2025). "For example, IL-6 signaling in macrophages is required for immunotherapy-driven tumor regression in murine tumor models." (PMID 39653766, 2025). "Restoration of IL-6 expression in these cells reinstated senescence and blocked tumor growth in NOD/SCID mice." (PMID 40643463, 2025).
tumor (continued). "The selection of specific cytokines (TNF-α, IFN-γ, IL-12, and IL-6) for assessing T-cell-mediated immune activation was guided by their established roles in anti-tumor immunity." (PMID 40722845, 2025). "As expected, we observed that β-glucan treatment induced a higher level of IL-1β, IL-6, and IL-12p70 in tumor microenvironment, and the enhanced cytokines production was inhibited by alisertib." (PMID 40920087, 2025). "The increase in PLR with increasing stage is related, firstly, to the increased production of thrombopoietin (TPO) and IL-6 by tumor cells and, secondly, to the fact that tumor cells directly stimulate platelets." (PMID 39940871, 2025). "Of the IL-6 family members found differentially expressed in the tumor, only IL-6 was significantly enriched in the serum, albeit at a relatively low absolute concentration (< 20 pg/mL)." (PMID 41278737, 2025). "NF-κB and IL-6/STAT3 form an inflammatory positive-feedback loop that promotes tumor survival and proliferation, while suppressing antitumor immunity and compromising microbicidal defenses at mucosal barriers." (PMID 41463208, 2025). "Having a new secretory profile, CAF produce elevated levels of IL-6 and other pro-tumorigenic cytokines and interact with tumor cells, which in turn secrete high levels of IL-6." (PMID 41303164, 2025). "A strong positive correlation has been established between serum IL‐6 levels and poor prognosis in patients with specific tumor types." (PMID 40620232, 2025). "Conversely, under pathological conditions, such as cancer cachexia, chronic IL-6 signaling induced by the presence of a tumor can promote osteoclastogenesis and enhance bone resorption." (PMID 40869331, 2025). "Overall, further research is needed to elucidate the precise conditions under which IL-6 either boosts or impairs tumor immunity, with the ultimate aim of limiting IL-6-targeting therapies to scenarios in which it enhances the response to cancer immunotherapy." (PMID 39653766, 2025). "Lastly, while this study established an association between IL-6 and the ESCC tumor microenvironment, further basic experiments are necessary to elucidate IL-6’s specific regulatory mechanisms within the ESCC tumor immune microenvironment in the future." (PMID 40433391, 2025). "Cancer-associated adipocytes secrete the chemokines CCL2/5 and IL-6/TNF-α, which promote tumour proliferation and immune escape by binding to CXCR2 and IL-6R/TNF-R on the surface of tumour cells." (PMID 40414892, 2025). "TAMs support tumor progression by secreting pro-migratory cytokines like IL-6 and induce tumor metastasis through PI3K/AKT and HIF-1a signalling." (PMID 40931345, 2025). "Second, H1975dnMCAK cells exhibited activation of cGAS–STING signaling and its downstream signaling, including tumor-promoting cytokine IL-6." (PMID 40136696, 2025). "STAT3, activated downstream of IL-6 or tumor-derived cytokines, orchestrates expression of arginase-1, IL-10, and CD163—key mediators of immunosuppressive reprogramming." (PMID 41459539, 2025). "By attenuating COX-2 expression, downregulating pro-inflammatory cytokines (TNF-α, IL-6), and interfering with phosphorylation-dependent transcriptional activation, pecan bioactives effectively reduce the tumor-promoting microenvironment." (PMID 41226270, 2025). "IL-6, produced by immune cells (mainly macrophages), tumor cells, and intestinal epithelial cells, orchestrates immune responses, regulates lymphocyte maturation, and contributes to macrophage differentiation." (PMID 41007818, 2025). "MMP2 and MMP9 produced by tumor cells are controlled by adipocyte-derived leptin and IL6 by activating FAK- and SRC-dependent pathways." (PMID 40841364, 2025). "Regarding chemoresistance, the production of TNF-α and IL-6 contributes to a tumor-promoting microenvironment." (PMID 40404908, 2025).
tumor (continued). "Although IL-6 typically mediates immune defense, accumulating evidence reveals its dual role in PC: directly promoting tumor proliferation/survival while driving immune escape via T cell exclusion and functional impairment." (PMID 40948749, 2025). "Firstly, miR-122 is a liver miRNA that is crucial for HBV infection, and it is downregulated by IL-6 and TNF-α, and its absence is associated with the promotion of tumor development, motility, and invasion." (PMID 40625740, 2025). "Here, we determined the levels of three relevant cytokines involved in tumor progression: (a) IL-2, (b) IL-6, and (c) TNF-α." (PMID 41155954, 2025). "TNBC cells secrete elevated levels of the pro-inflammatory cytokines IL-6 and IL-8, which are critical drivers of tumor progression." (PMID 40868199, 2025). "Their accumulation in the tumor mass correlates with high oncogenic cell cycle-related kinase (CCRK)/IL-6/CD11b/CD33 expression and poor prognosis." (PMID 40136652, 2025). "M1 macrophages limit tumor growth by secreting proinflammatory cytokines such as IL-6, IL-8, and TNF-α." (PMID 40070576, 2025). "Recent results from prospective clinical trials have also indicated that elevated IL-6 levels were related to tumor progression and poor survival outcomes in patients undergoing ICIs for colon cancer or advanced non–small cell lung cancer." (PMID 40160826, 2025). "The connection of IL-6 to tumor aggressiveness and disease stage progression makes itsuitable for serving as a standalone biomarker to track malignant advancement." (PMID 40978585, 2025). "Extensive evidence supports the role of IL-6 in driving tumor progression by inducing cancer cell proliferation and survival while simultaneously suppressing antitumor immunity." (PMID 39653766, 2025). "As a consequence of this immune activation, the tumor microenvironment becomes enriched with pro-inflammatory cytokines, such as interleukin-2 (IL-2), interleukin-6 (IL-6), interferon gamma (IFN-γ), and tumor necrosis factor alpha (TNF-α)." (PMID 40807154, 2025). "IL-6, a multifunctional cytokine, plays significant roles in chronic inflammatory diseases and promotes tumor cell proliferation, survival, angiogenesis, and immune tolerance." (PMID 40129920, 2025). "further identified tumor-derived IL-1α as an upstream mediator of PSC-driven IL-6 release and STAT3 activation in TME." (PMID 40948749, 2025). "Although the composition of ascites is heterogeneous, the presence of pro‐inflammatory, tumour‐enhancing and chemoresistance‐driving signalling molecules like IL‐6 has been reported in AAF." (PMID 39245677, 2025). "IL6 signaling pathways aid in maintaining tumor dormancy, potentially keeping the tumor clinically undetectable while still exerting immune pressure." (PMID 40427188, 2025). "miR‐203a‐3p in CAFs inhibits their phenotypic transition into inflammatory CAFs via the MyD88/NF‐κB/IL‐6 axis, subsequently reducing IL‐6 secretion and suppressing tumour progression." (PMID 40579785, 2025). "Tumor heterogeneity dictates that only a subset of tumor cells can promote platelet production through a positive feedback loop involving IL-6 secretion." (PMID 40547304, 2025). "Tumor-derived CXCL1 further activates STAT3/NF-κB pathway in adipocytes to promote IL6 expression and secretion in adipocytes, and finally forms a cascade of interaction." (PMID 40841364, 2025). "The tumor-only group also significantly increased IL-6 and TBAR levels in the plasma, as well as the IL-1β mRNA level in the gastrocnemius, compared to the control group (p < 0.001)." (PMID 40136406, 2025). "Functionally, our results showed that IL-6 production, a cytokine critical for tumor immunity, remained unchanged under the co-culture conditions." (PMID 41009763, 2025). "In CC clinical tissues, the expression of FXR has been negatively correlated with IL-6 levels, and the activation of FXR by obeticholic acid inhibits tumor growth and metastasis via IL-6 suppression." (PMID 40278303, 2025).
tumor (continued). "The presence of tumor cells was sufficient to upregulate several other pro-inflammatory cytokines and chemokines, including tumor necrosis factor alpha, IL-6, chemokine C-C motif ligand 3 (CCL3), and CCL4, regardless of anti-PD-L1 treatment." (PMID 41050935, 2025). "Tumor-secreted inflammation occurs due to the secretion of various inflammatory signal molecules by macrophages, such as interleukin-6 (IL-6), interleukin-1 (IL-1), and tumor necrosis factor-α (TNF-α)." (PMID 40865948, 2025). "Taken together, our results suggest that IL‐6 contributes to eribulin resistance through both direct effects on cancer cells and modulation of the tumor immune microenvironment." (PMID 41189442, 2025). "Metabolic regulators such as CPT1C in CAFs also promote IL-6 secretion, inducing an immunosuppressive M2-like macrophage phenotype and supporting tumor immune evasion." (PMID 40718440, 2025). "Inflammatory cells, such as macrophages, neutrophils, and lymphocytes, infiltrate the tumor microenvironment and secrete pro-inflammatory cytokines, including interleukin-6 (IL-6) and tumor necrosis factor-alpha (TNF-α)." (PMID 40428567, 2025). "Increases secretion of immune suppressive cytokines like TGF-β and IL-6, inhibiting anti-tumor immunity." (PMID 39911396, 2025). "Persistent activation of proinflammatory and proangiogenic pathways, including nuclear factor kappa B (NF-kB), interleukin 6 (IL-6), and interleukin 8 (IL-8), plays a crucial role in tumor progression." (PMID 41479792, 2025). "Cytokines such as TNF-α, TGF-β, IL-6, and IL-10 are pivotal players in these processes, driving inflammation, tumor progression, and immune suppression." (PMID 40933989, 2025). "IL-6 inhibition further promotes CD8+ T cell-dependent tumor elimination through the restoration of CD4+ T cell function in an IFN-γ-dependent manner." (PMID 41294748, 2025). "TGF-β and IL-6, influenced by circadian rhythms, are prone to dysregulation within the tumor immune microenvironment." (PMID 41376629, 2025). "Functionally, Δ18a enhanced invasive activity in vitro, while Δ14′ promoted osteoclast formation by increasing IL-6 and IL-8 secretion and contributed to bone metastasis by increasing tumour burden and osteolytic activity in vivo." (PMID 40427200, 2025). "Consistent with fibrate-mediated PPARα activation reducing IL-6 in vivo, we show that PPARα depletion or miR-BART20-3p overexpression both elevate IL-6 in GC cells, linking viral miRNA activity to inflammation-driven tumor progression." (PMID 40732023, 2025). "IL-6 also appears to be essential for the upregulation of E-selectin, P-selectin, L-selectin, and ICAM-1, as shown by IL-6 antibody-mediated blockade in multiple tumor models." (PMID 41375025, 2025). "In fact, IL6 levels reflect the complexity and severity of tumor immunogenicity within the OC-TME, with higher levels being more common in advanced stages." (PMID 40427188, 2025). "Based on this approach, TNF-α, IL-6 and IL-12 showed the highest discriminative ability between tumour and normal tissue (AUC 0.76, 0.65 and 0.65, respectively), while TGF-β1 and IL-1α yielded AUC values close to 0.5, indicating limited diagnostic value." (PMID 41465261, 2025). "Concentrations of mRNA and protein for the tumor cell promotor and inflammation mediator IL-6 and immunosuppressor and tumor promotor IDO1 were determined in MSC medium supernatants with and without cisplatin treatment." (PMID 40699630, 2025). "On the other hand, STING activation concurrently induces immunoregulatory cytokines, including IFN-γ and IL-6, which upregulate PD-L1 expression on both tumor and immune cells." (PMID 41204180, 2025). "By modulating the NF-κB pathway, AE can inhibit the expression of pro-inflammatory factors TNF-α and IL-6, hence lowering the inflammatory response in the tumor microenvironment and blocking tumor growth and metastasis." (PMID 41480347, 2025).
tumor (continued). "In this study, we investigated the expression levels of IL-2, IL-10, IL-6, and TNF-α and assessed their associations with clinical and pathological tumor features." (PMID 40869161, 2025). "IL‐6 is one of the significant cytokines present in the tumor microenvironment at high concentrations and is known to be upregulated in cancer." (PMID 39803280, 2025). "Anti‐IL‐6 antibodies were intriguing given the target's involvement in tumour growth, survival and IgM production, but when tested in WM patients, they did not provide enough efficacy to enter standard of care." (PMID 41447345, 2025). "IL-6 promotes tumor cell proliferation and inhibits apoptosis by activating the Janus kinase (JAK)-signal transducer and activator of transcription 3 (STAT3) pathway, further exacerbating CRC progression." (PMID 40995229, 2025). "The elevated IFN-γ secretion level and reduced levels of TNF-α and IL-6 detected in tumor tissues suggested that activated CIK cells infiltrated into tumors." (PMID 40539041, 2025). "Tumor tissues were collected for ex vivo mammosphere assays, miRNA expression analysis, and IL-6 detection by ELISA." (PMID 39896297, 2025). "IL6 gene expression was higher in the whole tumor tissue than in cancer cell-enriched samples obtained by laser capture microdissection (LCM)." (PMID 40143084, 2025). "Over the past decade, several CAFs-derived chemokines such as interleukin-6 (IL-6), C-X-C motif chemokine ligand 12 (CXCL12), and C-C motif chemokine ligand 2 (CCL2) have been implicated in the mechanisms driving tumor progression." (PMID 41408647, 2025). "COX-2 drives the expression of prostaglandins and creates a pro-tumour environment via the upregulation of immunosuppressive cytokines such as interleukin-10 (IL-10), and pro-inflammatory cytokines (such as IL-6)." (PMID 41463341, 2025). "These life-threatening events seem to be triggered by mediators of cellular communication within the tumour system, particularly a high level of IL-6, which activates STAT3 even in normal cells." (PMID 41009413, 2025). "This initiates signaling events that culminate to stimulate the LPS-induced MyD88 dependent production of IL-1β and IL-23 that differentiates IL-17-producing innate lymphoid cells to produce IL-6 and IL-17 during tumor-promoting events." (PMID 41376623, 2025). "Researchers have found that certain intra-tumor microorganisms can affect the production and secretion of cytokines, such as IL-6 and TNF-α." (PMID 40475759, 2025). "GSEAs of the tumor, liver, and skeletal muscle transcriptomics shared an enriched activation of the IL6/JAK/STAT3 pathway in mice with CACS." (PMID 41278737, 2025). "It promotes tumor cell proliferation and survival by interacting with IL-6 and other pro-inflammatory cytokines." (PMID 41426339, 2025). "IL-6 is pro-inflammatory cytokine involved in various cellular processes, including immune responses and tumor progression." (PMID 40307509, 2025). "Our findings demonstrate that CAFs critically contribute to L-OHP resistance in CRC, largely by modulating the tumor microenvironment through IL-6 secretion." (PMID 40718440, 2025). "The significantly higher IL-6 levels in CAF-derived CM compared to tumor cell-derived CM suggest that CAFs are a major source of IL-6 in the tumor microenvironment." (PMID 40718440, 2025). "Studies have shown that the activation of the IL‐6/STAT3 signaling pathway in tumor stromal cells, including CAFs, induces the secretion of miRNA‐214 in stromal‐derived EVs, thereby promoting tumor cell extravasation." (PMID 40656546, 2025). "We also analyzed the co-expression of CTCF and IL6 in different tumor regions using data from Xiao-Jun Ma and collaborators." (PMID 40143084, 2025). "IL-6 not only promotes the expression of anti-apoptotic proteins such as Bcl-xL and Mcl-1, which help tumor cells resist TNFα-induced apoptosis, but also further drives cell cycle progression by promoting the phosphorylation of STAT3." (PMID 41400642, 2025).